ABCD4 (ATP binding cassette subfamily D member 4)
Description:
Lysosomal membrane protein that transports cobalamin (Vitamin B12) from the lysosomal lumen to the cytosol in an ATP-dependent manner. Targeted by LMBRD1 lysosomal chaperone from the endoplasmic reticulum to the lysosomal membrane. Then forms a complex with lysosomal chaperone LMBRD1 and cytosolic MMACHC to transport cobalamin across the lysosomal membrane.
Synonyms: P70R; PMP69; PXMP1L; EST352188; ABC41; MAHCJ; P79R
Tractability: Small molecule: a structure with a bound ligand is known. Antibody: UniProt predicts a signal peptide or a membrane-spanning region. PROTAC: ubiquitination databases record sites on it.
Gene: Protein-coding gene on chromosome 14 (74,285,269 to 74,303,055, reverse strand). Ensembl gene ENSG00000119688.
Subcellular location: Endoplasmic reticulum membrane; Lysosome membrane
Pathways (Reactome):
Metabolism: Transport of RCbl within the body; Uptake of dietary cobalamins into enterocytes
Disease: Defective ABCD4 causes MAHCJ
Gene Ontology:
Molecular function: ABC-type vitamin B12 transporter activity; identical protein binding; protein binding; ATP binding; ATPase-coupled transmembrane transporter activity; long-chain fatty acid transmembrane transporter activity; ABC-type transporter activity; ATP hydrolysis activity
Biological process: cobalamin metabolic process; cobalamin transport; long-chain fatty acid import into peroxisome; peroxisome organization; transmembrane transport; very long-chain fatty acid catabolic process
Cellular component: endoplasmic reticulum membrane; lysosomal membrane; peroxisome; ATP-binding cassette (ABC) transporter complex; membrane
Genetic constraint (gnomAD): Loss-of-function variants: 51 observed, 83.42 expected, observed/expected ratio (o/e) 0.61, 90% interval 0.49 to 0.77. The upper end of that interval is the gene's LOEUF score, 0.77, which puts it in group 3 of 6, group 1 being the genes least tolerant of losing a copy. Missense variants: 731 observed, 771.42 expected, observed/expected ratio (o/e) 0.95, 90% interval 0.89 to 1.01. Synonymous variants: 322 observed, 318.03 expected, observed/expected ratio (o/e) 1.01, 90% interval 0.92 to 1.11.
Gene-disease validity (ClinGen):
ClinGen rates the evidence that ABCD4 causes each of these diseases.
methylmalonic acidemia with homocystinuria, type cblJ (autosomal recessive): Moderate.
Homologues: Orthologues: chimpanzee ABCD4 (99% identical), macaque ABCD4 (96% identical), mouse Abcd4 (90% identical), rat Abcd4 (89% identical), pig ABCD4 (88% identical), guinea pig ABCD4 (88% identical), rabbit ABCD4 (85% identical), zebrafish abcd4 (66% identical), tropical clawed frog abcd4 (61% identical), dog ABCD4 (44% identical), Caenorhabditis elegans pmp-3 (40% identical), Caenorhabditis elegans pmp-5 (33% identical). Paralogues in human: ABCD2 (28% identical), ABCD3 (28% identical).
Diseases named in the same sentence as ABCD4 in open-access papers:
ABCD4 is named in the same sentence as 16 diseases in open-access papers, as found by Europe PMC text mining. Sharing a sentence is not in itself a finding about the gene and the disease. The quoted sentences say what the papers report.
cobalamin deficiency (4 papers, 2016 to 2021). "To date, eight clinical mutations in the ABCD4 gene that result in cobalamin deficiency have been reported." (PMID 33845046, 2021). "Our findings give insight into the molecular mechanism of cobalamin transport by which ABCD4 involves and its importance in cobalamin deficiency." (PMID 33845046, 2021). "The dysfunction of ABCD4 results in a failure in lysosomal cobalamin release, which mimics the cobalamin deficiency caused by the defect of lysosomal membrane protein LMBD1." (PMID 27766264, 2016). "Recently, it is reported that ABCD3 and ABCD4 are responsible for hepatosplenomegaly and vitamin B12 deficiency, respectively." (PMID 27766264, 2016). "Mutation of either gene causes vitamin B12 deficiency and results in a similar defect of intracellular transport of cobalamin from lysosomes, suggesting ABCD4 and LMBD1 function in a coordinated manner." (PMID 27456980, 2016). "Moreover, insights into the molecular mechanisms of the effect of mutant ABCD4 reported in cobalamin deficiency are provided." (PMID 33845046, 2021). "Abcd4 is linked to vitamin B12 deficiency, which leads to a reduction in fat metabolism; the finding that Abcd4 was downregulated in the F0-HFD group (F0-HFD/F0-NC = 0.46) is consistent with the fact that it could cause or aggravate obesity." (PMID 28599310, 2017).
adrenoleukodystrophy (2 papers, 2016 to 2023). A peroxisomal disorder resulting in cerebral demyelination, axonal dysfunction in the spinal cord leading to spastic paraplegia, adrenal insufficiency and in some cases testicular insufficiency. "ABCD4 is a member of the superfamily of ATP-binding cassette (ABC) transporters involved in peroxisome biogenesis and adrenoleukodystrophy (ALD) disorder." (PMID 27289096, 2016).
colorectal cancer (2 papers, 2020 to 2023). A primary or metastatic malignant neoplasm that affects the colon or rectum. "Low transcript levels of this gene were also associated with shorter DFS of colorectal cancer patients and ABCD4 was among amplified genes in resistant cancer cell lines." (PMID 33334016, 2020). "Interestingly, Wrn, Abcd4, Ythdc2, and Dync1h1 within this group are noted to have oncogenic function in colon, breast, gastric, and colorectal cancers, respectively." (PMID 36765634, 2023).
hepatoma (1 paper, 2016). "To examine whether the subcellular localization of ABCD4 is shifted by the expression of LMBD1, we prepared human hepatoma HuH7 cells stably expressing ABCD4-HA, and then transiently expressed LMBD1 fused with GFP (LMBD1-GFP) in the cells." (PMID 27456980, 2016).
neural tube defect (1 paper, 2023). A congenital defect characterized by failure of the neural tube to close completely; this results in the presence of openings in the brain or spinal cord. "Vitamin B12 acts as a necessary cofactor in methionine synthase, and low vitamin B12 levels, particularly during development, have been linked to elevated incidences of neural tube defects in humans.The mutations in ABCD4 could potentially alter the expression or function of this gene." (PMID 37889833, 2023).
ovarian tumors (1 paper, 2020). "It served as an argument to weaken the case for ABCD4 and NF2 as oncogenic drivers of CABR18, given the discordant results found in her breast and ovarian tumors." (PMID 32295625, 2020).
cancer (3 papers, 2014 to 2025). A tumor composed of atypical neoplastic, often pleomorphic cells that invade other tissues. "Besides the fact that the ABCA subfamily’s role as lipid transporters, the specific functions of ABCA1, ABCA13, and ABCD4 in cancer and specifically GBM are relatively unknown, which might warrant closer and more in-depth studies." (PMID 39861164, 2025). "Using the datasets in The Cancer Genome Atlas and Gene Expression Omnibus, we found upregulated ABC transporters that either negatively impacted survival in univariate analyses (ABCA1, ABCA13, ABCB9, ABCD4) or were independent negative prognosis factors for patients with GBM (ABCA13, ABCB9)." (PMID 39861164, 2025).
ABCD4 also shares sentences with these, for which no sentence is quoted: homocystinuria (2 papers); Methylmalonic aciduria (2); anemia (1); autism (1); cardiovascular diseases (1); Hepatosplenomegaly (1); non-small cell lung carcinoma (1); Obesity (1); schizophrenia (1).